HMGB1 (high mobility group box 1)
Diseases named in the same sentence as HMGB1 in open-access papers (continued):
Sharing a sentence is not in itself a finding about the gene and the disease.
preeclampsia (17 papers, 2014 to 2025). Preeclampsia is a hypertensive disorder of pregnancy that is characterized by new-onset hypertension with proteinuria presenting after 20 weeks of gestation, and depending on mild or severe forms may initially present with severe headache, visual disturbances, and hyperreflexia. "Furthermore, CAV1 has been implicated in the mechanism of oedema in preeclampsia (PE) following hypoxia of trophoblasts through the HMGB1/TLR4/CAV-1 pathway." (PMID 32028606, 2020). "HMGB1 expression was increased in the cytoplasm of syncytiotrophoblast cells in preeclampsia placenta." (PMID 40291503, 2025). "The HMGB1–RAGE pathway is strongly associated with trophoblast damage, systemic inflammation, and the maternal endothelial pathology seen in preeclampsia." (PMID 40860347, 2025). "HMGB1 has been proved to be a key factor contributing to preeclampsia as a pro-inflammatory mediator." (PMID 35477735, 2022). "The inhibited pyroptosis on one hand promoted proliferation, migration and invasion of trophoblasts, and on the other hand promoted M2 and inhibited M1 polarization of macrophages in preeclampsia through decreasing the secretion of HMGB1." (PMID 36153499, 2022). "This study showed that serum HMGB1 at 16–20+6 weeks of gestation were effective in predicting preeclampsia." (PMID 35477735, 2022). "Further research into the use of serum HMGB1 levels to predict preeclampsia during the first trimester or in combination with other tests to improve the predictive value of preeclampsia would be interesting." (PMID 35477735, 2022). "When using abnormal serum HMGB1 levels combined with mean UAPI to predict preeclampsia, the sensitivity and specificity were 88.0% and 50.8%, respectively." (PMID 35477735, 2022). "Serum HMGB1 levels were significantly higher in overall and late-onset preeclampsia than in normal pregnant women." (PMID 35477735, 2022). "The objective of this study was to identify the predictive value for preeclampsia of second-trimester serum high mobility group box-1 (HMGB1) and uterine artery Doppler in singleton pregnancies." (PMID 35477735, 2022). "The strength of this study was that it is the first prospective study of HMGB1 and uterine artery Doppler in the second-trimester for preeclampsia prediction." (PMID 35477735, 2022). "In severe preeclampsia, there was an increase in gene expression of HMGB1 on trophoblasts as well as an increase in circulating HMGB1 levels in maternal serum." (PMID 35477735, 2022). "HO-1 and eNOS levels were decreased, and NLRP3 and HMGB1 levels were increased in the preeclampsia model, resulting in the elevation of oxidative stress and pyroptosis in the preeclampsia model." (PMID 36153499, 2022). "The inhibited pyroptosis on one hand promoted proliferation, migration, invasion and fusion of trophoblasts, and on the other hand promoted M2 and inhibited M1 polarization of macrophages in preeclampsia through decreasing secretion of HMGB1." (PMID 36153499, 2022). "Several studies have reported that HMGB1 levels are elevated in patients with pregnancy complicated by gestational diabetes mellitus, preeclampsia, and preterm prelabor rupture of membranes." (PMID 35003098, 2021). "Next, we compared HMGB1 levels in early-onset versus late-onset PE in order to highlight a possible relation between HMGB1 expression and gestational age during preeclampsia." (PMID 29149067, 2017). "Recently, two isoforms of HMGB1 (28 and 30 kDa) have been characterized in human placenta and were shown to be highly expressed in preeclampsia." (PMID 29410969, 2017). "However, preeclamptic placentas secrete higher levels of IL1β into the maternal circulation and key components of the inflammasome including ASC, cleaved caspase-1, GSDMDNT, and HMGB1 are increased in the placenta from women with preeclampsia." (PMID 37292200, 2023).
preeclampsia (continued). "However, our study found that the serum HMGB1 levels was elevated prior to the onset of preeclampsia symptoms, making it as one of the possible serum markers that can predict preeclampsia." (PMID 35477735, 2022). "The sensitivity of serum HMGB1 level in combination of UAPI to predict preeclampsia was high." (PMID 35477735, 2022). "Similarly, our study also found an elevation of oxidative stress-induced pyroptosis in both in vitro and in vivo preeclampsia models, which inhibited the proliferation, migration, and invasion of trophoblasts, and M2 polarization via secretion of HMGB1." (PMID 36153499, 2022). "HMGB1 and its receptors were found in high concentrations in the serum and trophoblastic cytoplasm of pregnant women with preeclampsia, particularly in those with severe symptoms and preeclampsia that began before 34 weeks of gestation." (PMID 35477735, 2022). "As a result, HMGB1 has been considered as a crucial role in the pathogenesis of preeclampsia." (PMID 35477735, 2022). "Previously, serum HMGB1 levels were found to be increased at the time of preeclampsia diagnosis." (PMID 35477735, 2022). "Thus, the primary objective of this study was to determine the predictive value of HMGB1 and uterine artery Doppler in the second-trimester for preeclampsia in singleton pregnancy." (PMID 35477735, 2022). "If a better understanding of the rise of HMGB1 in early pregnancy before clinical preeclampsia occurs, further research into intervention or prevention strategies could be possible." (PMID 35477735, 2022). "Moreover, increased level of HMGB1 was detected in sera of patients suffering from severe preeclampsia." (PMID 29410969, 2017). "Furthermore, in research on the pathophysiology of pre-eclampsia (PE), hypoxic trophoblasts displayed higher intracellular HMGB1 protein levels which could increase TLR4 and Caveolin-1." (PMID 31284269, 2019). "The HMGB1–RAGE and S100–RAGE axes play pivotal roles in preeclampsia by mediating placental and systemic inflammation, endothelial dysfunction, and anti-angiogenic pathways." (PMID 40860347, 2025). "When using abnormal serum HMGB1 levels combined with mean UAPI above 95th percentile, the sensitivity, specificity, PPV and NPV to predict preeclampsia were 88.0%, 50.8%, 10.8% and 98.4%, respectively." (PMID 35477735, 2022). "Serum HMGB1 levels and mean uterine artery pulsatility index (UAPI) were combined to calculate the predictive value for preeclampsia." (PMID 35477735, 2022). "Moreover, damage-associated molecular patterns (e.g., high-mobility group box-1 protein (HMGB1) and the extra domain A of fibronectin (EDA)) released from tissues damaged in the response to preeclampsia can also activate neutrophils." (PMID 35563315, 2022). "According to the study, serum HMGB1 levels in the second-trimester with or without uterine artery Doppler were effective in predicting preeclampsia." (PMID 35477735, 2022). "This study found that early-onset preeclampsia had higher HMGB1 level than control, however there was not statistically difference between two group." (PMID 35477735, 2022). "Third, serum HMGB1 levels may rising non-specifically to preeclampsia therefore interpretation should be cautious, and HMGB1 should not be used as a single screening test for predict preeclampsia." (PMID 35477735, 2022).
Hepatic steatosis (16 papers, 2015 to 2025). Steatosis is a term used to denote lipid accumulation within hepatocytes. "Mice with liver-specific Hmgb1 deficiency display exacerbated liver steatosis, while Hmgb1-overexpressing mice exhibited a protection from fatty liver progression when subjected to nutritional stress." (PMID 35333579, 2022). "HMGB1 is a damage‐associated molecular pattern (DAMP) molecule that triggers the progression of hepatic steatosis by inducing signals upon interaction with RAGE." (PMID 32936538, 2020). "To further explore the role of HMGB1 on liver lipid synthesis, and firmly establish HMGB1 as a potent candidate to repress liver steatosis, we set up a gain-of-function model where HMGB1 is overexpressed in vivo using adeno-associated virus (AAV)–mediated gene transfer." (PMID 35333579, 2022). "Thus, we examined whether nuclear HMGB1 expression is associated with HFD/STZ-induced hepatic steatosis." (PMID 28798347, 2017). "Exosomes in the intestine of HFD mice enhanced the release of HMGB1, which can be transported from the intestine to the liver through exosomes, leading to hepatic steatosis in ecological disorders." (PMID 40129979, 2025). "Together, our data reveal a novel role of HMGB1 in alleviating liver steatosis through the repression of the LXRα/PPARγ axis during metabolic stress." (PMID 35333579, 2022). "At least in the in vivo context of liver steatosis, our results support a minor role for HMGB1 in regulating nucleosomal landscapes, which represents a significant layer of epigenetic control of transcription." (PMID 35333579, 2022). "Together, these findings suggest that hepatocellular HMGB1 protects from liver steatosis development." (PMID 35333579, 2022). "In the ASC−/- mice on a high-fat diet (HFD), Chen and colleagues identified a DAMP molecule high-mobility group protein B1 (HMGB1) as a “cargo” transported by exosomes from the intestine to the liver, triggering hepatic steatosis." (PMID 36052075, 2022). "As LXRα is a key lipogenic TF involved in cholesterol metabolism and liver lipogenesis, the derepression of its activity induced by HMGB1 deletion logically translates into liver steatosis." (PMID 35333579, 2022). "We found that OA/PA‐induced lipid accumulation was alleviated by AG and HMGB1 siRNA, demonstrating that both AGE and HMGB1 play important roles in RAGE‐mediated hepatic steatosis." (PMID 32936538, 2020). "We found that haploinsufficiency of TonEBP suppressed the HFD/STZ-induced upregulation of HMGB1 in hepatic nuclei and attenuated hepatic steatosis." (PMID 28798347, 2017). "As LXRα and PPARγ are key lipogenic TFs involved in cholesterol metabolism and liver lipogenesis, the potential derepression of their activity induced by HMGB1 deletion could translate into liver steatosis." (PMID 35333579, 2022). "In addition, it was found that intestinal flora disorders in MAFLD abnormally increased the Bacteroidetes ratio and Streptomyces spp., and that high mobility group box 1 (HMGB1) promoted hepatic steatosis through transfer from the intestine to the liver." (PMID 35634340, 2022). "Indeed, GLC suppresses the process of liver injury from hepatic steatosis to steatohepatitis by blocking inflammatory response through the HMGB1-directed pathway." (PMID 36278177, 2022). "Nuclear form of HMGB1 in hepatocytes protects from liver steatosis development." (PMID 35333579, 2022). "In addition, in the study of MAFLD (NAFLD) characterized by hepatic steatosis and inflammation, Sal B can also inhibit the migration and release of high mobility group protein 1 (HMGB1) by upregulating SIRT1 expression." (PMID 33343348, 2020). "Therefore, we aimed to investigate the role of hepatocyte-specific HMGB1 (HC-HMGB1) in development of hepatic steatosis." (PMID 33238880, 2020). "We speculate that old mice with a large number of senescent liver cells might secrete HMGB1 which activates the RAGE/PPARα axis to promote hepatic steatosis." (PMID 32936538, 2020).
Hepatic steatosis (continued). "Therefore, three-dimensional conformation and RNA binding represent additional mechanisms by which HMGB1 could mediate its repressive effect on LXRα, which will therefore be worthwhile to further investigate in the context of liver steatosis." (PMID 35333579, 2022). "In patients with decreased hepatic steatosis, we found lower baseline levels of profibrotic, proinflammatory, and pro-apoptotic platelet-derived TGF-1, HMGB1, and pCXCR4." (PMID 40860949, 2025). "In dysbiosis, exosomes act as the transporter of high mobility group box 1 (HMGB1) protein from the intestine to the liver, triggering hepatic steatosis." (PMID 39144666, 2024). "We are the first to demonstrate that the SIRT1/HMGB1 pathway is a key therapeutic target for controlling NAFLD inflammation and that SalB confers protection against HFD- and PA-induced hepatic steatosis and inflammation through SIRT1-mediated HMGB1 deacetylation." (PMID 26525891, 2015). "Bioinformatic and biochemical findings show that ALDH2, Niemann pick C1 (NPC1), and high mobility group protein 1 (HMGB1), which are responsible for lipid degradation and lipid homeostasis, may represent new therapeutic targets of calycosin in treatments against hepatic steatosis." (PMID 41463300, 2025).
Hypoglycemia (16 papers, 2014 to 2025). A decreased concentration of glucose in the blood. "This gap in the knowledge can be attributed to the lethality associated with global HMGB1 knockout mice, which results from hypoglycemia." (PMID 38187339, 2024). "HMGB1 is essential for life, because HMGB1-deficient mice die within 24 h of birth due to hypoglycemia." (PMID 33396481, 2020). "These functions are essential for survival, as HMGB1-deficient mice die of hypoglycemia within 24 hours after birth." (PMID 24690901, 2014). "Deletion of HMGB1 disrupts cell growth and causes lethal hypoglycemia in mouse pups." (PMID 37903777, 2023). "This is primarily due to the lethality of global embryonic HMGB1 deletion, with hypoglycemia being a significant factor contributing to mortality in mice." (PMID 38187339, 2024). "A study reported death of HMGB1‐knockout mice from hypoglycemia 24 h after their birth, and the mice exhibited defects in the glucocorticoid receptor transcriptional function, which highlights the life‐supporting function of HMGB1." (PMID 37062906, 2023). "HMGB1 global knockout mice die shortly after birth due to the downregulation of glucocorticoid receptor and subsequent hypoglycemia, suggesting a critical role for HMGB1 in sustaining life." (PMID 25126737, 2014). "The occurrence of hypoglycemia in the context of global embryonic HMGB1 deletion highlights the potentially critical role HMGB1 might play in glucose metabolism." (PMID 38187339, 2024). "Absence of HMGB1 in global knockout mice is lethal within a few days of birth, with newborn knockout mice succumbing to hypoglycemia, although HMGB1 can be inducibly knocked out globally in adult mice, suggesting a specific role for HMGB1 in development and early metabolism." (PMID 33238880, 2020). "The levels of NT-probNP, HMGB1, ACTA and the incidence of hypoglycemia were the highest in the severe group, which were significantly higher than those in the moderate group and mild group (P<0.05)." (PMID 36577981, 2022). "The levels of NT-probNP, HMGB1, ACTA and the incidence of hypoglycemia were the lowest in the mild group." (PMID 36577981, 2022). "HMGB1 also has a cytokine function in the cell, and the absence of HMGB1 is lethal in knockout mice due to hypoglycemia." (PMID 41009989, 2025). "The full scope of HMGB1 functions could not be verified in vivo, as HMGB1-knockout mice die from fatal neonatal hypoglycemia." (PMID 40362460, 2025).
liver failure (16 papers, 2011 to 2025). A liver disease characterized by the liver losing or has lost all of its function. "HMGB1 plays predominant role in etiology of liver failure in chronic HBV individuals by impeding immunological activity of regulatory T cells and by down-regulating Foxp3 expression." (PMID 36895013, 2023). "The treatment of mice with neutralizing antibodies (specific for HMGB1) protected the liver, prevented liver failure, and improved the survival rate of the animals." (PMID 36016387, 2022). "The TNF‐α/HMGB1 inflammation signalling pathway plays an important role in pyroptosis during liver failure and AKI." (PMID 32419317, 2020). "When hepatic failure occurs, HMGB1 can be constitutively expressed and passively released from damaged cells or actively secreted from activated immune cells." (PMID 29967293, 2018). "HMGB1 has been demonstrated to be a good therapeutic target for treating liver failure." (PMID 32431618, 2020). "Moreover, the experiment targeting HMGB1 demonstrated it was a good therapeutic target for liver failure (LF)." (PMID 32431618, 2020). "Recently, HMGB1 has been recognized as a therapeutic treatment for hepatic failure." (PMID 31771292, 2019). "Consequently, we employed a murine model of ALF induced by co-administration of D-GalN and LPS to further investigate the translocation of HMGB1 in hepatocytes during liver failure/injury." (PMID 21406085, 2011). "Given the huge numbers of hepatocytes in the liver, potential HMGB1 release by hepatocytes could contribute to the pathogenesis of liver failure/injury." (PMID 21406085, 2011). "Furthermore, a positive correlation was observed between circulating HMGB1 levels and its transcript, indicating that hepatocyte damage during infection is directly related to high levels of circulating HMGB1, suggesting that this protein is a possible marker of liver failure." (PMID 36016387, 2022). "However, increasing evidence indicate that HMGB1 may be involved in the pathological progress of liver failure." (PMID 34904016, 2021). "However, previous studies have mostly focused on the role of HMGB1 as a pro-inflammatory factor, but in addition to inflammation, excessive apoptosis is also an important mechanism of cell death in liver failure." (PMID 32431618, 2020). "Indeed, circulating HMGB1 levels were found to be elevated in patients suffering from liver failure caused by hepatitis B (data not shown)." (PMID 21406085, 2011). "In conclusion, the significance of this study lies in the computational delineation of novel, intertwined circuits and common dynamic network patterns involving GDF-15, HMGB1, and MIG in the context of inflammation and liver failure." (PMID 40809145, 2024). "Researchers showed that HMGB1 and TLR4 were reported to be closely related to inflammation and liver failure." (PMID 33959665, 2021). "A positive correlation was found between serum HMGB1 levels and the degrees of brain failure or coagulation failure but not liver failure." (PMID 36712653, 2022). "In normal healthy controls or patients with chronic HBV infection but not liver failure, HMGB1 staining was mostly localized in the nucleus, with few cells occasionally positive for cytoplasmic HMGB1." (PMID 21406085, 2011). "To evaluate the possibility of HMGB1 cytoplasmic translocation in ALF, we determined whether HMGB1 is released in hepatocytes and end organ in patients with liver failure/injury." (PMID 21406085, 2011).